CD151 (CD151 molecule (Raph blood group))
Diseases named in the same sentence as CD151 in open-access papers (continued):
Sharing a sentence is not in itself a finding about the gene and the disease.
infection (20 papers, 2008 to 2025). The state of being infected such as from the introduction of a foreign agent such as serum, vaccine, antigenic substance or organism. "The association with integrins is crucial, as CD151 mutants incapable of binding to integrins are unable to recover susceptibility to infection in CD151 depleted cells." (PMID 32210347, 2020). "The association of viral particles with CD151 was also evident in intracellular compartments seven hours after infection." (PMID 24553111, 2014). "The association with CD151 was also sustained in intracellular endosomes near the nucleus later in infection." (PMID 18836553, 2008). "Similar to CD151, integrin α6 and perhaps also integrin α3 are implicated in the infection process of HPV16; it is tempting to speculate that these proteins assemble on the cell-surface to form a viral entry platform." (PMID 32210347, 2020). "We tested the gene expression of several tetraspanins and identified only CD151 to be selectively and significantly upregulated in both mosquito cells (Aag-2 and C6/36 cells) and in EVs derived from these cells and upon infection with ZIKV and DENV2." (PMID 40806523, 2025). "QRT-PCR analysis showed that Aag-2 cells treated with only 2 μg of CD151 antibody (for 4 h) followed by ZIKV/DENV2 infection (at 5 MOI, for additional 24 h) significantly reduced the viral loads in comparison to the isotype control antibody treatment." (PMID 40806523, 2025). "Immunoblotting analysis correlated with QRT-PCR data, where dramatically increased CD151 protein levels were evident upon ZIKV or DENV2 infection in C6/36 cells when compared to the levels noted in their respective uninfected controls." (PMID 40806523, 2025). "Direct physical interactions of CD151 revealed an important function of this tetraspanin in facilitating ZIKV/DENV2 infection in mosquito cells." (PMID 40806523, 2025). "A similar experiment but using DENV2 infection indicated a TCID50 value of 6.13 × 104 pfu/mL for the CD151-antibody-treated group, while the isotype-antibody-treated control group showed a TCID50 value of 1.09 × 105 pfu/mL." (PMID 40806523, 2025). "We believe that the expression of CD151 in EVs at later time points in ZIKV/DENV2 infection suggests a role for this tetraspanin in the exit process or exocytosis via EVs." (PMID 40806523, 2025). "Compelling evidence indicates that the large extracellular loop (LEL) of mast cell-expressed TET proteins [Cluster of differentiation (CDs), such as CD9, CD63, CD81, CD82, CD151] plays a key role in the route of pathogens infection." (PMID 35310653, 2022). "In this study, the general requirements of the tetraspanins CD9, CD63, CD81, and CD151 in infections by the most oncogenic HPV type, HPV16, were tested as previously investigated for HCMV." (PMID 30279342, 2018). "We found that the C-terminal tails of CD63 and CD151 significantly inhibited infections of both HPV16 and HCMV." (PMID 30279342, 2018). "In summary, the C-terminal peptides of tetraspanins CD63 and CD151 showed the strongest effects on infection rates." (PMID 30279342, 2018). "Mechanistically, we show that the CD63 and CD151 C-terminal peptides decreased the disassembly of HPV16 capsids which consequently inhibited infection." (PMID 30279342, 2018). "Papillomavirus types 16, 18, and 31 require the tetraspanin CD151 during cell entry, and the CD151 C-terminal domain and juxtamembrane palmitoylation sites are critical for infection." (PMID 29677132, 2018). "It has been observed that only a few viral particles were colocalized with CD151 at the early time points of HeLa cells infection (up to 10 minutes), but as the infection process proceeded further, colocalization of CD151 and HPV16-L1 was increased." (PMID 24553111, 2014). "To examine whether ZIKV/DENV2 infection also modulates cd151 gene expression in A. albopictus cells, we infected the C6/36 cell line and collected both cells and EVs at days 1, 3, and 5 post-ZIKV/DENV2-infection." (PMID 40806523, 2025).
infection (continued). "However, integrin α3 is required for endocytosis as its depletion reduces all virus post-binding steps such as the PsVs induced reduction of the CD151 cell-surface level, L1 cleavage, capsid disassembly and infection rate." (PMID 32210347, 2020). "Furthermore, recovery experiments using C-terminally truncated CD151 emphasized the importance of the cytoplasmic domain in virus entry by its inability to restore HPV16 disassembly and infection in CD151-depleted cells." (PMID 30946955, 2019). "Interestingly, infection of cells with VSV, which is known to be infectious and pathogenic in humans, also led to the downregulation of CD9, CD81, CD151 and EGFR." (PMID 29121670, 2017). "Indeed, it has been demonstrated, that siRNA mediated depletion of CD151, α3β1 and α6 integrin complexes in different cell lines reduced the infection of HPV16." (PMID 24553111, 2014). "The strongest reduction of infection in both cell lines was found with anti-CD151." (PMID 18836553, 2008). "However, as seen with CD63, we detected increasing colocalization of HPV16 particles with CD151 on the cell surface as the infection process proceeded." (PMID 18836553, 2008). "Again, cells were treated with control or CD151 specific antibodies prior to infection." (PMID 18836553, 2008). "Moreover, additional receptors might be involved in this complex entry process, particularly in the context of Marc-145 cells, where simian vimentin and CD151 have been implicated as potential contributors to PRRSV entry and infection." (PMID 40146709, 2025). "Higher CD151 expression was consistently observed in T cells from women with the CC genotype where endometrial infection was reduced, suggesting that CD151 may play a protective role during Ct infection." (PMID 36248887, 2022). "Aag-2 cells (1 × 106 cells/well) were transfected with mock (empty pL4440 plasmid) or cd151 dsRNA (750 ng/well for each) and lipofectamine for 48 h followed by ZIKV/DENV2 infection (5 MOI/2 MOI) for an additional 24 h." (PMID 40806523, 2025). "The cd151 transcript levels were significantly upregulated at all tested time points of days 1, 3, and 5 post-DENV2-infection in C6/36 cells." (PMID 40806523, 2025). "To characterize the role of CD151 protein in facilitating ZIKV and DENV2 infection and exosome-mediated transmission, we analyzed the direct interactions of the CD151 protein with ZIKV and DENV2 in C6/36 cells infected with 5 MOI of the respective viruses." (PMID 40806523, 2025). "Full-length immunoblots and total protein profile gel images for CD151 expression upon ZIKV and DENV2 infection are shown." (PMID 40806523, 2025). "Moreover, the improper function of TEMs caused by the CD151 downregulation might not directly affect the activation of neutrophils and monocytes, possibly ensuring the neutrophils’ normal function against infection after ischemia." (PMID 34022890, 2021). "For example, EGF increases the infection rate of ADAM17-depleted cells, EGF increases the proximity between L1 and CD151 after ADAM17 knockdown, and ADAM17 knockdown diminishes the overlap between L1 and EGFR." (PMID 31107240, 2019). "Here, we studied plasma membrane dynamics of CD151 and EGFR and the HPV16 capsid during the early phase of infection." (PMID 31107240, 2019). "The LELs of CD63, CD81 and CD151 induced a minor, but significant reduction of HPV infection rates in HeLa and HaCaT cells at 24 h post infection (h.p.i.)." (PMID 30279342, 2018). "Knockdown of CD63 displayed a reduction of infection by more than 50% and CD9 knockdown resulted in a strong inhibition of about 90%, which was comparable to results obtained by CD151 siRNAs." (PMID 30279342, 2018). "Infection with HCMV TB40 and HSV-1 downmodulated the tetraspanins CD81, CD151, and CD9, as well as EGFR." (PMID 29121670, 2017).
infection (continued). "Overall, these data indicate that CD151 could directly interact with the ZIKV NS2B and DENV2 capsid proteins, and both viral E-proteins perhaps to facilitate the infection, transmission, and survival of these flaviviruses in mosquito cells." (PMID 40806523, 2025). "siRNAs targeting CD151 and CD63 served as a control for impaired infection." (PMID 30279342, 2018). "When we studied the localization of pseudovirions relative to CD151, we again found almost no colocalization on the plasma membrane at early stages of infection (10 min)." (PMID 18836553, 2008). "Perhaps, the putative mediator CD151, integrin and vimentin expressed in non-infected PGE may be associated with PRRSV viral entry and host response during the early stage of infection." (PMID 37099541, 2023). "In conclusion, these data show downregulation of CD9, CD81, CD151, and EGFR upon infection with two herpesviruses, two orthopoxviruses and a negative strand RNA virus, suggesting that the reduction of cell surface expression of these molecules is common upon infection." (PMID 29121670, 2017).
adenocarcinoma (3 papers, 2020 to 2024). A common cancer characterized by the presence of malignant glandular cells. "The study used retrospective analysis to examine 157 adenocarcinoma biopsy specimens and 199 patient cases from The Cancer Genome Atlas, correlating CD151 expression with patient survival." (PMID 38982031, 2024). "In this study, we aim to fill this knowledge gap by investigating the clinical and functional impact of CD151 expression in two cohorts of adenocarcinoma patients and NSCLC models without EGFR mutations." (PMID 38982031, 2024).
colorectal (3 papers, 2014 to 2022). "This study demonstrated CEACAM6, LGR5 and Wnt pathway suppression by CD151 silencing might occur through TGFβ1 regulation, offering a comprehensive view of CD151's roles in colorectal carcinogenesis." (PMID 33767593, 2021).
digestive system cancer (1 paper, 2024). A primary or metastatic malignant neoplasm involving any part of the digestive system. "Generally, the expression of CD9, CD151, Tspan1, Tspan5, Tspan8, Tspan12, Tspan15, and Tspan31 are upregulated, facilitating the migration and invasion of digestive system cancer cells." (PMID 38389703, 2024).
digestive system tumors (1 paper, 2024). "Numerous recent studies have demonstrated that CD151 plays a carcinogenic role in digestive system tumors." (PMID 38389703, 2024). "Conversely, CD9, CD151, Tspan8, Tspan1, Tspan5, Tspan31, Tspan12, and Tspan15 are upregulated and enhance digestive system tumor cell metastasis." (PMID 38389703, 2024).
respiratory diseases (1 paper, 2020). "Given the importance of CD151 in respiratory diseases, it is interesting to note that little is known about regulators of CD151 expression changes." (PMID 32117989, 2020). "Furthermore, CD151 monoclonal antibodies, gene deletion, and nanotechnology studies support the notion for its development as a novel targeted or adjuvant therapy in the treatment of respiratory diseases." (PMID 32117989, 2020).
CD151 also shares sentences with these, for which no sentence is quoted: cervical cancer (2 papers); fibrosarcoma (2); invasive ductal carcinomas (2); renal failure (2); airway hyperresponsiveness (1); anaplastic ependymoma (1); bacterial infection (1); cardiac hypertrophy (1); clear cell carcinoma (1); cutaneous squamous cell carcinoma (1); deafness (1); diabetic nephropathy (1); end-stage renal failure (1); endometrioid carcinoma (1); fungal infection (1); gallbladder carcinoma (1); hereditary nephrotic syndrome (1); idiopathic pulmonary fibrosis (1); Infertility (1); influenza (1); interstitial cystitis (1); intrahepatic cholangiocarcinoma (1); lymph node metastasis (1); malignant glioma (1); metastasis (1); Nail dystrophy (1); neuroblastoma (1); papillary serous adenocarcinomas (1); papilloma (1); prostate (1).
A further 6 diseases each share a sentence with CD151 in 1 paper.